RPS16P9 (ribosomal protein S16 pseudogene 9)
Gene: Processed pseudogene on chromosome 19 (45,332,698 to 45,333,124, reverse strand). Ensembl gene ENSG00000242675.
Diseases named in the same sentence as RPS16P9 in open-access papers:
RPS16P9 is named in the same sentence as 1 disease in open-access papers, as found by Europe PMC text mining. Sharing a sentence is not in itself a finding about the gene and the disease.
RPS16P9 shares sentences with these, for which no sentence is quoted: ovarian carcinoma (1 paper).